BNIP5 (BCL2 interacting protein 5)
Synonyms: C6orf222; DKFZp779B1540
Tractability: PROTAC: UniProt records ubiquitination sites on it.
Gene: Protein-coding gene on chromosome 6 (36,315,757 to 36,337,010, reverse strand). Ensembl gene ENSG00000189325.
Subcellular location (Human Protein Atlas): Cytosol
Gene Ontology:
Molecular function: protein binding
Genetic constraint (gnomAD): Loss-of-function variants: 56 observed, 62.93 expected, observed/expected ratio (o/e) 0.89, 90% interval 0.72 to 1.11. The upper end of that interval is the gene's LOEUF score, 1.11, which puts it in group 4 of 6, group 1 being the genes least tolerant of losing a copy. Missense variants: 800 observed, 819.65 expected, observed/expected ratio (o/e) 0.98, 90% interval 0.92 to 1.03. Synonymous variants: 306 observed, 324.71 expected, observed/expected ratio (o/e) 0.94, 90% interval 0.86 to 1.04.
Homologues: Orthologues: chimpanzee BNIP5 (98% identical), macaque BNIP5 (89% identical), pig BNIP5 (61% identical), dog BNIP5 (60% identical), rabbit BNIP5 (52% identical), mouse Bnip5 (48% identical), rat Bnip5 (47% identical).
Diseases named in the same sentence as BNIP5 in open-access papers:
BNIP5 is named in the same sentence as 2 diseases in open-access papers, as found by Europe PMC text mining. Sharing a sentence is not in itself a finding about the gene and the disease. The quoted sentences say what the papers report.
tumor (1 paper, 2023). "However, the effect of BNIP5 on tumor progression has not been reported, and this study demonstrated for the first time that BNIP5 methylation may also be related to chemotherapy response in GC." (PMID 37771430, 2023).
BNIP5 also shares sentences with these, for which no sentence is quoted: Giardia infections (1 paper).